NAT2 (N-acetyltransferase 2)
Diseases named in the same sentence as NAT2 in open-access papers (continued):
Sharing a sentence is not in itself a finding about the gene and the disease.
gastric cancer (4 papers, 2007 to 2022). A primary or metastatic malignant neoplasm involving the stomach. "GSTT1, SULT1A1 and NAT2 polymorphisms appear to modulate individual's susceptibility to gastric cancer in this Italian population, particularly when more than one unfavourable genotype is present, or when combined with cigarette smoke." (PMID 17996038, 2007). "The gene-gene interaction analyses demonstrated that individuals with combined GSTT1 null and NAT2 slow acetylators had an additional increased risk of gastric cancer, with an OR of 3.00 (95%CI: 1.52–5.93) and an AP of 52%." (PMID 17996038, 2007). "This study suggests that in this Italian population, GSTT1, SULT1A1 and NAT2 polymorphisms may modulate an individual's susceptibility to gastric cancer, particularly when more than one unfavourable genotype is present and in combination with cigarette smoke." (PMID 17996038, 2007). "Among the main results of our study, we found that GSTT1 null genotype individuals contemporarily NAT2 slow acetylators have a strongly increased risk of gastric cancer, with a more than just the additive effect of the risks associated with each of the two inherited SNPs." (PMID 17996038, 2007). "On the basis of ARP and PARP associated with SNPs of gastric cancer, the top three for ARP were 53.91% (NAT2, rs1799929), 53.05% (NAT2 phenotype), and 42.85% (IL-10, rs1800896)." (PMID 34491229, 2021). "In another study in the Kashmir Valley, none of the three NAT2 polymorphic alleles (rs1799929, rs1799930 and rs1799931) was found to be independently associated with risk of esophageal and gastric cancers, which was also in accordance with our results." (PMID 24586291, 2014). "In other words, since biological interaction among two causes occurs when the effect of one is dependent from the presence of the other, in the absence of either of the two components (GSTT1 null or NAT2 slow), than a substantial number of gastric cancer cases would not occur." (PMID 17996038, 2007).
Hypertension (4 papers, 2018 to 2025). The presence of chronic increased pressure in the systemic arterial system. "The potential benefits of using NAT2 genotype‐informed phenotype to guide hydralazine therapy are to achieve effective blood pressure reduction in the setting of resistant hypertension and minimize the incidence of drug‐induced SLE." (PMID 40974042, 2025). "RCC risk has been found to be associated with interactions between alcohol consumption and ADH726; sodium and hypertension and AGTR, AGT and ACE31; calcium and vitamin D intake and RXRA28; tobacco smoking and NAT2, CYP1A1 and GSTM125; and meat-cooking mutagens and ITPR2 and EPAS127." (PMID 31924838, 2020).
Insulin resistance (4 papers, 2017 to 2022). Increased resistance towards insulin, that is, diminished effectiveness of insulin in reducing blood glucose levels. "NAT2 is associated with insulin resistance, and deficiency of the mouse orthologue (i.e., NAT1) has also been associated with mitochondrial dysfunction." (PMID 35259281, 2022). "Another study has linked NAT2 with increased insulin resistance that is prevalent in type 2 diabetes patients and is a known risk factor for CVD." (PMID 28931094, 2017). "Previous research identified that NAT2 is also associated with insulin resistance." (PMID 36536295, 2022). "This shared association of insulin resistance as well as SAF with NAT2 may, in part, be explanatory for the predictive value of SAF for type 2 diabetes development." (PMID 36536295, 2022). "Deficiency of this gene causes mitochondrial dysfunction with decreased cellular respiration and ATP generation, suggesting that NAT2 may mediate insulin resistance and mitochondrial dysfunction by binding key regulators of energy balance." (PMID 35884374, 2022).
leukemia (4 papers, 2015 to 2023). A malignant (clonal) hematologic disorder, involving hematopoietic stem cells and characterized by the presence of primitive or atypical myeloid or lymphoid cells in the bone marrow and the blood. "Notwithstanding, after multiple comparison tests, the statistical significance remained only for NAT2*11A, NAT2*12C, and NAT2*5V alleles, which were less frequent in healthy children than in cases with leukemia." (PMID 33072605, 2020). "A study conducted in infant leukemia with maternal exposure to dipyrone during pregnancy reported that NAT2 SNPs are associated with this malignancy regardless of maternal exposure to the medication." (PMID 33072605, 2020).
pulmonary tuberculosis (4 papers, 2013 to 2026). A bacterial infection that affects the lungs and is caused by Mycobacterium tuberculosis. "The purpose of this study was to elucidate whether stratified medicine based on the NAT2 gene polymorphism could improve the tolerability and efficacy of multidrug therapy for pulmonary tuberculosis with INH." (PMID 23150149, 2013). "In the present study we have demonstrated the significant therapeutic potential of the NAT2 genotype-guided dosing of INH in the intensive phase of the internationally standardized 6-month four-drug regimen for newly diagnosed pulmonary tuberculosis." (PMID 23150149, 2013). "This study is a pharmacogenetic clinical trial designed to clarify whether the N-acetyltransferase 2 gene (NAT2) genotype-guided dosing of isoniazid improves the tolerability and efficacy of the 6-month four-drug standard regimen for newly diagnosed pulmonary tuberculosis." (PMID 23150149, 2013).
acute leukemia (3 papers, 2020). A clonal (malignant) hematopoietic disorder with an acute onset, affecting the bone marrow and the peripheral blood. "Recently, a research group reviewed the published literature on the correlation between NAT2 genetic variants and susceptibility to acute leukemia and it was reported that rs1801280 (341T>C (NAT2∗5)) contributes to the disease." (PMID 32626768, 2020).
acute lymphoblastic leukemia (3 papers, 2020). Leukemia with an acute onset, characterized by the presence of lymphoblasts in the bone marrow and the peripheral blood. "Distribution of the most frequent NAT2 alleles in health children and in patients with acute lymphoblastic leukemia." (PMID 33072605, 2020). "Genotype and alleles frequency of NAT2, NQ01, and CYP2E1 polymorphisms in children with acute lymphoblastic leukemia and controls." (PMID 33072605, 2020). "Gene-gene interaction analysis between NAT2, NQ01, and CYP2E1 polymorphisms and acute lymphoblastic leukemia risk." (PMID 33072605, 2020).
colorectal adenoma (3 papers, 2012 to 2021). An adenoma that arises from the colon or rectum. "Meta-analyses assessing the association of NAT2 variants with colorectal adenomas were conducted and subgroup analyses on smoking status and the source of the controls were also performed." (PMID 23226745, 2012). "In conclusion, the data of the present study suggested that NAT2 polymorphisms may be a risk factor for colorectal adenomas in individuals who have a history of smoking." (PMID 23226745, 2012). "Whether NAT2 polymorphisms are a risk factor for colorectal adenoma remains uncertain." (PMID 23226745, 2012). "A case-control study of colorectal adenoma tested for interaction between HAA intake and NAT2 acetylation genotype on the risk of colorectal adenoma." (PMID 34315542, 2021). "In the present study, the overall data of the meta-analyses showed that the NAT2 polymorphism may not have a significant association with colorectal adenoma risk." (PMID 23226745, 2012).
hepatocellular carcinoma (3 papers, 2005 to 2024). A malignant tumor that arises from hepatocytes. "Transient transfection of hsa-miR-15a-3p in hepatoma cell lines (Huh7 and HepG2 cells) showed that hsa-miR-15a-3p suppressed NAT2 production significantly." (PMID 34888351, 2021). "Similarly, western blot assays showed that endogenous NAT2 protein levels were significantly reduced in hepatoma cells treated with exogenous hsa-miR-15a-3p mimics, compared to the control group." (PMID 34888351, 2021).
lung adenocarcinoma (3 papers, 2006 to 2024). A carcinoma that arises from the lung and is characterized by the presence of malignant glandular epithelial cells. "Some other research articles reported that the combined NAT2/CYP1A2 status was related to lung adenocarcinoma." (PMID 25915206, 2015).
malnutrition (3 papers, 2015 to 2025). Inadequate nutrition resulting from poor diet, malabsorption, or abnormal nutrient distribution. "The variables that remained in the model, thus increasing the chance of hepatotoxicity were the use of fluconazole, malnutrition (BMI <18.5) and being phenotypically classified as NAT2 slow acetylators." (PMID 27332812, 2016).
agranulocytosis (2 papers, 2024 to 2025). "Although pharmacogenetic testing was not performed in this case, genome-wide studies have identified associations between metamizole-induced agranulocytosis and polymorphisms in HLA-B*27:05, NAT2, and cytochrome P450 isoenzymes." (PMID 41267696, 2025).
asthma (2 papers, 2019 to 2024). "We have earlier observed in a study population of 182 workers exposed to di-isocyanates, 109 of whom had earlier been diagnosed with asthma, that genetic factors, especially the GSTM3 and NAT2 genotypes, modified risk for occupational asthma and allergic responses to di-isocyanate exposure." (PMID 31649932, 2019). "Importantly, this is a novel NAT2 variant that is not a part of any named alleles and has been shown in one study to be significantly associated with the risk of aspirin-intolerant asthma." (PMID 38375040, 2024).
autoimmune disease (2 papers, 2016 to 2018). A disorder resulting from loss of function or tissue destruction of an organ or multiple organs, arising from humoral or cellular immune responses of the individual to their own tissue constituents. "There are a number of studies showing that NAT2 gene polymorphisms lead to increased susceptibility to various diseases, primarily cancer and autoimmune disorders." (PMID 29992137, 2018). "There is a great deal of research on the possible association of NAT2 gene polymorphisms with other autoimmune diseases." (PMID 29992137, 2018).
chronic kidney disease (2 papers, 2015 to 2017). Impairment of the renal function secondary to chronic kidney damage persisting for three or more months. "In conclusion, the combination of end-stage renal disease, removal of pyridoxal phosphate by hemodialysis, and deleterious NAT2 polymorphisms, contributed to the severe toxicity of isoniazid in our patient." (PMID 28870161, 2017). "The following case illustrates the impact of end-stage renal disease and NAT2 polymorphisms on the risk of isoniazid toxicity, and discusses how these life-threatening complications may be prevented and managed." (PMID 28870161, 2017). "The present case illustrates the risk of potentially life-threatening toxic side effects of isoniazid in patients at risk, including end-stage renal disease patients on dialysis and/or those harboring a slow acetylator phenotype conferred by NAT2 polymorphisms." (PMID 28870161, 2017).
chronic periodontitis (2 papers, 2003 to 2022). A chronic inflammatory process that affects the tissues that surround and support the teeth. "Subjects designated as so-called 'rapid acetylators' (bearing at least one wild-type allele NAT2*4) or bearing the highly expressed MPO variant (homozygous -463 G/G) are at an increased risk of periodontitis when smoking." (PMID 19570260, 2003). "The incidence of individual NAT2 genotypes in chronic periodontitis was assessed, for which smoking may also be a risk factor." (PMID 35454140, 2022). "Other enzymes whose gene polymorphisms were studied for association with periodontitis include the angiotensin-converting enzyme (ACE) and N-acetyltransferase (NAT2)." (PMID 35454140, 2022).
colorectal tumor (2 papers, 2020). "We identify and describe the effect of a compound that impairs the growth of colorectal tumors with slow NAT2 activity by half when compared to wild-type." (PMID 32944621, 2020). "To identify compounds that selectively kill colorectal tumors with slow NAT2, we genetically engineered the human CRC cells RKO and DLD-1 to express the rapid or slow NAT2 enzymatic variants." (PMID 32944621, 2020). "The resolution of NAT2 haplotypes is critical for understanding whether a colorectal tumor has undergone LOH and is eligible for APA treatment." (PMID 33384440, 2020). "Given that ~ 21% of colorectal tumors undergo LOH at 8p2223, we estimate that ~ 79,000 individuals heterozygous for a NAT2 slow allele could potentially be eligible for therapy every year (given an annual incidence of 1.3 million CRC cases)." (PMID 33384440, 2020).
dyslipidemia (2 papers, 2023 to 2024). "Although variable NAT2 activity has been linked to physiologically and clinically relevant outcomes (e.g., drug toxicity and dyslipidemia), few studies have investigated its transcriptional regulation." (PMID 39624836, 2024). "A couple of coding (rs1208-A; RAF 0.68) and non-coding (rs4921913-C; RAF 0.35) NAT2 SNPs also have been linked to metabolic disorders, i.e., insulin resistance and metabolic syndrome, respectively." (PMID 37077812, 2023). "In summary, some of the risk alleles for dyslipidemia or cardiometabolic disease also have been associated with differential urinary or serum metabolite levels which are indicative of relative NAT2 activity." (PMID 37077812, 2023). "Non-coding NAT2 variants also have been associated with increased cardiovascular medication usage, which indirectly supports that dyslipidemia conferred by risk alleles of NAT2 variants can result in clinically pathological conditions." (PMID 37077812, 2023). "How do non-coding or intergenic NAT2 variants confer risk of dyslipidemia and cardiometabolic disease?" (PMID 37077812, 2023). "Variants that are linked to differential urinary or serum metabolite levels also support the idea that the dyslipidemia risk alleles are associated with high NAT2 activity." (PMID 37077812, 2023). "Recent studies and genome wide association studies have reported that genetic variants of NAT2 are associated with differential risks of developing dyslipidemia and cardiometabolic disorders, suggesting a previously unrecognized role of NAT2 in pathophysiology of metabolic disorders." (PMID 39624836, 2024). "The dyslipidemia risk alleles of non-coding NAT2 variants are associated with rapid NAT2 acetylator phenotype, suggesting that differential systemic NAT2 activity might be a risk factor for developing dyslipidemia." (PMID 37077812, 2023). "In other words, the dyslipidemia risk allele, rs1495741-G, is associated with relatively high NAT2 activity in human hepatocytes, although the mechanism is presently unknown." (PMID 37077812, 2023). "Analysis of these genetic variants, that are associated with both dyslipidemia and differential serum or urine metabolite levels (e.g., rs35570672-T), demonstrate that the risk alleles of NAT2 for dyslipidemia are associated with higher NAT2 activity (i.e., rapid NAT2 acetylator phenotype)." (PMID 37077812, 2023). "Moreover, the risk alleles for dyslipidemia (e.g., rs1495741-G) are associated with rapid NAT2 acetylator phenotype, suggesting that increased systemic NAT2 activity contributes to increases in plasma lipid and cholesterol levels." (PMID 37077812, 2023). "Taken together, half of non-coding or intergenic variants of NAT2 associate with dyslipidemia." (PMID 37077812, 2023). "We speculate that the association between two NAT2 variants (rs35570672 and rs146812806) and mean corpuscular hemoglobin level is reflective of the dyslipidemia and coronary artery disease risk associated with the haplotype." (PMID 37077812, 2023). "Interestingly, the risk alleles for dyslipidemia of NAT2 gene (e.g., rs1495741-A) are associated with the rapid acetylator phenotype in humans, which suggests that individuals with increased levels of NAT2 activity are at a higher risk of developing dyslipidemia." (PMID 39624836, 2024). "Although experimental evidence is lacking, the dyslipidemia risk alleles have been associated with rapid NAT2 acetylator phenotypes (i.e., relatively high NAT2 activity)." (PMID 37077812, 2023). "Regardless of the diet, rapid acetylator rats (with higher NAT2 activity) were more prone to develop dyslipidemia overall." (PMID 37077812, 2023).
heart failure (2 papers, 2023 to 2025). Inability of the heart to pump blood at an adequate rate to meet tissue metabolic requirements. "Future studies are warranted to study a possible association of NAT2 with heart failure and cardiac dysfunction." (PMID 36346460, 2023).
hepatotoxicity (2 papers, 2014). Toxicity that causes injury to the liver or impairs the liver function. "The proportion of patients with NAT1 and NAT2 genes predictive of slow acetylation phenotype was not statistically significantly different between the patients who developed TMP/SMX-related hepatotoxicity and those who did not." (PMID 25184238, 2014).
oesophageal cancer (2 papers, 2014 to 2015). "The G191A variant (NAT2*5 allele) was associated with reduced risk of oesophageal cancer among mixed ancestry individuals (OR = 0.68; 95%CI = 0.52–0.88; p = 0.004)." (PMID 24550997, 2014). "We hypothesized that NAT1 and NAT2 genetic polymorphisms may influence the risk of oesophageal cancer upon exposure to environmental carcinogens." (PMID 25886288, 2015). "Dr Matejcic concluded that NAT1 and NAT2 acetylation polymorphisms might have an important role in modifying the interaction between environmental risk factors and oesophageal cancer risk in black and mixed ancestry South Africans." (PMID 24550997, 2014). "NAT1 and NAT2 acetylation phenotypes were not independently associated with oesophageal cancer risk in both population groups." (PMID 24550997, 2014).
Parkinson's (2 papers, 2006 to 2025). "We found 13 original published association studies dealing with NAT2 gene polymorphisms in Parkinson's disease (see Background)." (PMID 16571112, 2006). "Several association studies have been undertaken on NAT2 sequence variations and Parkinson's disease, but results are conflicting." (PMID 16571112, 2006). "Apparently, there appears to be no overall association of NAT2 slow acetylator genotypes to Parkinson's disease." (PMID 16571112, 2006).
presbycusis (2 papers, 2014 to 2017). Bilateral hearing loss caused by progressive degeneration of cochlear structures and central auditory pathways, typically associated with the aging process. "They studied a population of 68 white individuals of Turkish descent with presbycusis and found that the risk for presbycusis was 15.2-fold higher among individuals with the mutant allele NAT2*6A than among those with a wild-type genotype (P = .013)." (PMID 25140308, 2014). "The frequency of the NAT2*6A mutant genotype (heterozygous and null genotype combined) was more frequent among patients with presbycusis (60%) than in controls (34%; P = 0.0086, OR = 2.88, 95% confidence interval [95% CI] = 1.355–6.141)." (PMID 25140308, 2014). "Here we explore the relationships between presbycusis, tinnitus, co-morbidities, and the genotypes of GRM7 and NAT2, in a sample of older Portuguese adults." (PMID 29163129, 2017). "Other studies considering different NAT2 alleles reported negative associations with ARHL and with the shape of the audiograms, when considering audiometric patterns of presbycusis in older individuals." (PMID 29163129, 2017).